CD68 (CD68 molecule)
Diseases named in the same sentence as CD68 in open-access papers (continued):
Sharing a sentence is not in itself a finding about the gene and the disease.
tumor (continued). "This is the first time showed that a fraction of OSCC tumor cells exhibited definite CD68 and CD163 expression." (PMID 26769084, 2016). "So we further combined TNM stage and densities of CD68 and IL-13 in tumor stroma to construct a united model for ESCC prognosis prediction, which proved to can provide more accuracy prognosis prediction for ESCC patients after operation." (PMID 26771842, 2016). "As expected, FACS analysis showed an increase in CD206+CD68+ M2a phenotype cells in sST2 low-expressing tumours." (PMID 27882929, 2016). "Distribution densities of CD1A, IL-13 and CD68 in tumor stroma of 66 ESCC patients were further calculated with InFormTM 2.0.1 software." (PMID 26771842, 2016). "Tumor progression significantly increased the tumor-infiltration of CD68+ macrophage, but slightly enhanced F4/80+ macrophages." (PMID 27656328, 2016). "High GATA3 expression correlated with poor survival in PTCL patients and with tumor-associated macrophage (TAM) infiltration, as indicated by the presence of CD68-positive cells." (PMID 27589565, 2016). "A high CD68:CD8 ratio implies a macrophage population suppressing the CD8 cytotoxic T-cells (e.g. M2-like) while a low score implies CD8+ T-cells mediated tumour suppression (e.g. M1-like)." (PMID 26943587, 2016). "Instead, a reverse result was observed in tumor stroma, a higher infiltrating density of CD68+ macrophages correlated with a better OS (median OS: 2.60 vs. 1.45 years, P = 0.0407)." (PMID 27736796, 2016). "We also found that patients with high density of tumor stroma CD68 positive cells had long overall survival in ESCC especially at TNM stage I, II and III." (PMID 26771842, 2016). "Next we performed co-immunofluorescence staining of AEG-1 and CD68 in sections of non-tumor tissue and tumor tissue samples." (PMID 27793010, 2016). "CD31 and CD68 constitute prognostic markers in patient subgroups that vary according to tumor compartment and stromal density." (PMID 27637082, 2016). "The results revealed that the numbers of CD68-positive macrophages was significantly increased in RCC tissues compared to those in surrounding non-tumor tissues." (PMID 27283897, 2016). "Here, typical CD68+ and F4/80+ macrophage subtypes and their tumor infiltration were assessed in HCC-bearing mice in response to inCVAX treatment." (PMID 27656328, 2016). "The number of CD68-positive macrophages in the nest and stroma of tumor was increased in 59 % (75 out of 127) and 66 % (84 out of 127) of samples, respectively." (PMID 26769084, 2016). "We observed a direct correlation between interim PET score and CD68 cell counts in the tumor biopsy." (PMID 26758564, 2016). "The distribution of CD11c‐positive macrophages, CD206‐positive macrophages and CD68‐positive macrophages in each tumour was forcefully correlated (P < 0.001, r = 0.462; P < 0.001, r = 0.978)." (PMID 26843477, 2016). "Only high tumor (intraepithelial) compartment expression of CD68 predicted for worse PFS (p = 0.033) and DMFS (p = 0.047), whereas no other significant findings were found for CD20." (PMID 27637082, 2016). "We further found that distribution densities of CD68 and IL-13 in tumor stroma area were positively correlated with ESCC patients’ overall survival after operation." (PMID 26771842, 2016). "Here we showed that, when compared to HGSOC (n = 55), LGSOC patients (n = 25) exhibited lower density of tumor-infiltrating CD68+ macrophage, along with an attenuated M2-skewed (CD163+) phenotype." (PMID 27462782, 2016). "We report that the number of CD68+ tumor‐infiltrating macrophages and presence of B‐symptoms are prognostic markers in ABVD‐treated HL also in the era of interim PET, while changes in TARC levels do not add prognostic information." (PMID 26758564, 2016).
tumor (continued). "Highly expressed inflammatory factors such as IL‐1β and TNF‐α, markers of inflammatory cells such as CD68 and CD11b, and massive inflammatory cells tracked by fluorescence in necrotic tumor tissue were detected in the tumor tissue of this model." (PMID 27734611, 2016). "CD68+ cell counts appear as the most reproducible and simple prognostic marker reflecting tumor biology and is currently available, using routine diagnostic methods." (PMID 26758564, 2016). "Large numbers of CD68+ cells were observed infiltrating tumor tissues and nearby stroma, whereas there were very few macrophages scattered throughout normal lymph node tissues." (PMID 27589565, 2016). "The results of our meta-analysis indicate an association between increased density of both CD68+ and CD163+ TAMs in the tumor microenvironment of adult cHL and poor outcome." (PMID 27745550, 2016). "Our results demonstrated that a high density of either CD68+ or CD163+ TAMs in the tumor microenvironment significantly predicted poor OS and shorter PFS for adult cHL (P = 0.000 and P = 0.000, respectively)." (PMID 27745550, 2016). "The role of CD68+ TAMs in both tumor islet and stroma on overall survival (OS) was studied in 9 articles." (PMID 27144518, 2016). "Instead, high tumor compartment CD68 expression predicted for worse outcome in the entire cohort, similar to stromal compartment CD68 infiltration in loose density tumors." (PMID 27637082, 2016). "The same holds true for human tumor-infiltrating myeloid cells, as, for example, human TAMs are often characterized by CD68, a receptor that is also expressed by other stromal tumor populations." (PMID 27065074, 2016). "We observed CD68 positive cells unevenly distributed in the lumen of the follicles or interspersed between the tumor cells, but rarely appeared in non- neoplastic thyroid tissues." (PMID 26875556, 2016). "The immune cells recruited to the tumor included cells expressing markers CD68, CD163, CD4, and CD25." (PMID 26964534, 2016). "Clearly, LNT significantly increased CD3 and CD68 expressions of tumor tissues on day 6 and day 8, and inhibited tumor cell proliferation from day 6 (Ki67 staining)." (PMID 27353254, 2016). "In tumor tissues, the number of CD68 positive cells (median, 67 cells/field) was higher than CD86 positive (median, 37 cells/field, p < 0.001) and CD206 positive cells (median, 33 cells/field, p < 0.001)." (PMID 26938527, 2016). "SAA protein expressions in tumor cells and in macrophage were both correlated with CD68+ macrophage infiltration in tumor tissue." (PMID 27058895, 2016). "In the whole slide specimens, tumor infiltration by APCs was associated with poorer 5 yr-EFS, including CD1a+ DCs (28.3% vs. 83.9%, p = 0.001) and CD68+ macrophages (45.5% vs. 84.4%, p = 0.032)." (PMID 27456063, 2016). "Although total expression of these markers lacked prognostic value in the entire cohort, nevertheless, high tumor compartment CD68 expression correlated with worse PFS (p = 0.033) and DMFS (p = 0.047)." (PMID 27637082, 2016). "TSPO expression in tumour sections as well as in LPS-induced inflammation brain sections was determined by CD68 immunohistochemical staining." (PMID 26853260, 2016). "Based on different infiltrating densities of CD57+ NK cells and CD68+macrophages in tumor nest, patients were divided into four subgroups and analyzed by a Cox model." (PMID 27736796, 2016). "We therefore examined if there was a difference in macrophage density (CD68) in prostates conditioned with the different tumor EVs." (PMID 27550147, 2016). "For AT-1 tumor-bearing prostates (TINT) the density of CD68+ cells was correlated to micro- and macro-vascular BrdU-labeling (Rs = 0.82 and Rs = 0.68, respectively, p<0.05)." (PMID 26536349, 2015). "Tumor sections were co-stained with antibodies against E-cadherin, CD68 and CD45 to label epithelial tumor cells, macrophages and leukocytes respectively." (PMID 26109430, 2015).
tumor (continued). "A subset of these patients had tumor samples available for assessment of CD68+ cell infiltration (n = 76)." (PMID 25738355, 2015). "Nevertheless, previous immunohistochemical studies addressing the role of macrophages in tumour microenvironment have largely relied on the use of CD68 and/or CD163 only and have considered CD163 to be a marker of M2 macrophages." (PMID 25978381, 2015). "In our cohort, immunohistochemistry managed to depict CD68-positive infiltrates comprising up to 20–50% of the individual tumor samples." (PMID 25807228, 2015). "This was also confirmed by immunofluorescence staining where tumour cells are labelled with the anti-GFP antibody (green) and tumour infiltrating human macrophages with anti-CD68 (red)." (PMID 26284300, 2015). "NF-κB and CD68 were highly expressed in mice treated with MCM, and were positively associated with tumor volume." (PMID 26010447, 2015). "We demonstrate that the intracerebral administration of BDNF induces reduction of tumour size and inhibition of M/Mφ infiltration and activation (as CD68 staining)." (PMID 25818172, 2015). "Low density of CD68+ or CD163+ macrophages in four combined areas was closely associated with more frequent low-grade histology and the intestinal type tumor of the Lauren classification." (PMID 26714314, 2015). "High numbers of CD68+ macrophages and MAC387+ macrophages were associated with a higher pT category and tumor grade." (PMID 26197470, 2015). "Double-staining immunohistochemistry of CD163/p-STAT, CD68/pSTAT1, CD163/c-MAF, and CD68/c-MAF was performed on tumor samples taken at the time of diagnosis." (PMID 26335330, 2015). "Compared to the AT-1 tumors, G tumors recruited a substantial number of CD68+ macrophages into the tumor." (PMID 26536349, 2015). "The CD3+ T cells were the most abundant in all tumor locations (at the invasive front, stroma and intraepithelial), followed by infiltrating CD68+ monocyte–macrophage and CD15/FUT4+ neutrophils, respectively." (PMID 26427914, 2015). "The density of CD68+ macrophages was especially high in pathological tumor stage 4 (pT4) tumor lesions compared with pT1 lesions." (PMID 26226629, 2015). "Distributions of tumour macrophage number (CD68 expression) categorisations according to clinical-pathological and molecular parameters (percentages in parenthesis)." (PMID 26008983, 2015). "Immunohistochemistry revealed the expression of CD68, which is one of the markers of osteoclasts in osteoclast-like giant cells in the tumor." (PMID 25793139, 2015). "CD7 and CD2 are expressed in varying degrees, and in approximately half of all cases, tumor cells are CD68+ and exhibit a specific cytoplasmic granular shape (i.e., multifocal color imaging of the Golgi apparatus)." (PMID 25663917, 2015). "A higher number of CD68+ cells was correlated with larger tumour size, higher TNM stages and Her-2 positivity." (PMID 25685069, 2015). "Among the 32 tumors of the discovery set, 23 (72 %) of CD15/FUT4-positive tumors were classified as low or high and had a higher recurrence than other tumor-related immune antigen i.e., CD68, CD73." (PMID 26427914, 2015). "There was a trend towards a higher number of positive cells for CD68 than CD163 (pro-tumor macrophages) in tumors both before and after the administration of 177Lu-BR96." (PMID 26374556, 2015). "There were few macrophages that were positive for CD68 in noncancerous colonic mucosa; however, there was a large number of CD68-positive macrophages in tumor regions." (PMID 25596747, 2015). "One-hundred-seventeen tumor samples were simultaneously informative for CD68, HLADR and ALDH1 stainings." (PMID 26305673, 2015). "The increased expressions of CD56 and CD68 indicated theactivated local immune microenvironment against tumor." (PMID 25928327, 2015). "hMCP1 siRNA-DOPC nanoparticles significantly abrogated daily restraint stress-induced tumor growth and inhibited infiltration of CD68+ and F4/80+ cells." (PMID 25738355, 2015).
tumor (continued). "A cytotoxic tumor microenvironment, defined by a CD8+/FOXP3+ ratio >1.5 was associated with higher numbers of CD68+pSTAT1+ (P=0.025) and CD163+pSTAT1+ macrophages (P<0.0005)." (PMID 25978381, 2015). "Immunohistochemical staining in the tumor cells is variously positive for S100, CD68, CD45, and CD20." (PMID 25889780, 2015). "As with the protein data, grade 3 tumours showed significantly higher expression of the macrophage marker CD68." (PMID 26008983, 2015). "The increase in tumor growth in response to daily restraint stress was also accompanied by increased infiltration of CD68+ cells, but this effect was blocked by hMCP1 siRNA-DOPC." (PMID 25738355, 2015). "Tumor macrophages as indicated by CD68+ cells in let-7d overexpressing xenografts were decreased by 52.7% as compared with the controls." (PMID 25193015, 2014). "In contrast, the number of CD68-positive macrophages infiltrating the tumor was higher and also significantly increased in TRX-EDA vaccinated individuals." (PMID 25360764, 2014). "Surprisingly, in GBMs treated with oncolytic viruses, both phagocytic marker CD68 and tumor suppressive macrophage marker CD163 were elevated in subpopulations of TAMs." (PMID 24675569, 2014). "Signal intensity formicroglial markers IA-IE and CD68 was significantly higher in the fluoxetine groupthroughout the entire area we examined (up to 400 μm distance from the tumor, p< 0.001)." (PMID 25129445, 2014). "The importance of the percentage of M2 macrophages of the total macrophage count (i.e. the CD163/CD68 ratio) and M1/M2 ratio has been found in other tumor types recently, such as melanoma, non-small cell lung carcinoma and angioimmunoblastic T-cell lymphoma." (PMID 25192022, 2014). "Immunocytochemical stains were performed on the cell block and the tumor cells stained positively with CD1a, S-100, and CD68." (PMID 24587931, 2014). "By immunohistochemistry, S100 can be used for diagnosis, supporting neural origin, and distinguishing GCTs from other neoplasms with abundant eosinophilic granular cytoplasm, and CD68." (PMID 25068699, 2014). "Immunohistochemistry, which was performed by envision method, of tumor showed that the tumor spindle cells were positive for vimentin, CD68, and Ki-67 (labeling = 18%)." (PMID 25379319, 2014). "Tumor free (n = 37) and metastatic (n = 17) lymph nodes of T1 and T2 oscc patients were processed for immunohistochemistry to detect CD68, CD11c, CD163 and MRC1 positive cells." (PMID 25042135, 2014). "While in galectin-3-expressing microenvironments, it was possible to observe CD68-positive cells infiltrating the tumor mass, these cells were only found in the periphery of galectin-3 negative tumors engrafted in KO mice." (PMID 24421272, 2014). "To assess the correlation between the expression of TAM and CSC markers in human OSCCs, we stained the tumor sections from human tissue arrays for OSCC with antibodies for CD68, CD163, SOX2, ALDH1, and CD44 and compared them with normal oral mucosa samples." (PMID 24883329, 2014). "Because the highest uPAR-scores were obtained for macrophages in both tumor core and at the invasive front, we scored macrophages (CD68-positive cells) according to size on specimens from 201 patients." (PMID 24889870, 2014). "Strikingly, many MCC contained a pronounced CD68+ cell presence, probably marking mature macrophages, which in some cases exceeded lymphocyte numbers and extended from the septa into the tumour." (PMID 24961933, 2014). "The presence of CD68 positive cells in all the analyzed tumor samples, albeit in different amount, suggest the relevance of activated microglia/macrophages in the human pathology as well." (PMID 24689533, 2014). "In analogy to the findings in tumor free lymph nodes a significantly decreased CD11c/CD68 and a significantly increased CD163/CD11c and MRC1/CD11c ratio was detected in the L1 cases compared to the L0 cases." (PMID 25042135, 2014).
tumor (continued). "DC101 significantly inhibited the CPA-stimulated tumor recruitment of macrophages (CD68 marker), dendritic cells (CD74 marker), and NK cells (NKp46 marker) and their cytotoxic effectors, perforin, granzymes, and lysozymes." (PMID 24965046, 2014). "In our study, we selected two alternative mask pairs: tumor (cytokeratin) and macrophage (CD68+) for the HGF analysis and tumor (cytokeratin) and stroma (vimentin+) for the c-Met analysis." (PMID 24952592, 2014). "Immunohistochemistry showed that the tumor spindle cells were positive for vimentin, CD68, CD45, and Ki-67 (labeling = 18%), α-smooth muscle antigen, and NSE." (PMID 25379319, 2014). "An additional study has indicated that tumors implanted into pre-irradiated fields grow slower than in unirradiated control tissues (i.e., the “tumor bed effect”) and demonstrate an aggregation of CD68+ TAMs in hypoxic regions." (PMID 23882218, 2013). "Immunohistochemical expression of CD68 was detected in the cytoplasm of morphologically heterogeneous mononuclear cells scattered within the tumor tissue, as single cells or groups of cells, only occasionally localized in perivascular areas." (PMID 24098347, 2013). "Immunoperoxidase stainings showed tumor cells with uniform cytoplasmic reactivity for vimentin, calponin, and CD68." (PMID 23628229, 2013). "Immunostaining on consecutive sections of tumor tissue and peritumoral liver tissue also showed that the density of CD163+ cells was much higher than that of the CD68+ cells both in tumor and in peritumoral liver tissue." (PMID 23555776, 2013). "The density of CD68-positive macrophages in the hypoxic region of the primary tumor core was also increased after RT." (PMID 23940516, 2013). "In the present study, similar to the Try+ McMD analysis, the test for the CD68+ MphMD-grouped data showed certain differences with regard to the tumor stage." (PMID 24137338, 2013). "In the present study, 19F MRI as well as the histological examination of mock-infected tumors revealed a diffuse distribution of both the 19F signal and the CD68+-macrophages throughout the tumor." (PMID 23441176, 2013). "To confirm the MRI results, we performed immuno-histological analysis of the CD68+-macrophage population in tumor sections at all time points." (PMID 23441176, 2013). "In cohort 1, the density of CD163+ cells was positively correlated with that of CD68+ cells in tumor tissue (r = 0.417, P<0.001) and peritumoral liver tissue (r = 0.565, P<0.001)." (PMID 23555776, 2013). "Analysis of the CD68-fluorescence signal intensity of whole tumor cross-sections by histology revealed a significantly enhanced fluorescence intensity in VACV-infected compared to mock-infected tumors (n = 3, p = 0.026)." (PMID 23441176, 2013). "The average densities of CD163 and CD68 staining were 0.023±0.034 and 0.011±0.023 in tumor, respectively, and 0.037±0.040 and 0.020±0.020 in peritumoral liver tissue, respectively." (PMID 23555776, 2013). "In our own current practice, we carry out double-labelling for MGMT and "cocktail" (CD34, CD45 and CD68) to come to an initial conclusion as to the likely methylation status of the tumour." (PMID 24252243, 2013). "A positive correlation between the levels of sIL-2R in sera and the numbers of CD68 positive macrophages in the tumor microenvironment was confirmed in FL and extranodal DLBCL." (PMID 24236041, 2013). "The relationship between TAMs and Bmi1 expression was analyzed by immunohistochemistry and quantitative real-time PCR (qRT-PCR), and results showed a positive correlation with tumor-infiltrating macrophages (CD68 and CD163) and Bmi1 expression in cancer cells." (PMID 24312366, 2013). "Nevertheless, the most relevant finding was the association between high CD68/(CD3+CD20) ratio and the expression of MMP-11 (stromalysin-3) or TIMP-2 by the MICs at the tumor center." (PMID 23300781, 2012).